RYR2 (ryanodine receptor 2)
Diseases named in the same sentence as RYR2 in open-access papers (continued):
Sharing a sentence is not in itself a finding about the gene and the disease.
left ventricular hypertrophy (2 papers, 2021 to 2025). Enlargement of the LEFT VENTRICLE of the heart. "Mice homozygous for the p.P1124L mutation in the RyR2 gene developed left ventricular hypertrophy, which was mediated by cardiac CALM overexpression." (PMID 40705464, 2025).
melanoma (2 papers, 2020 to 2024). A malignant, usually aggressive tumor composed of atypical, neoplastic melanocytes. "In contrast, the cardiac mRNA expression of Ryr2 was increased in anti-PD-L1-treated B16F10-GCV and in GCV mice compared to isotype Ctrl demonstrating that anti PD-L1 per se may mediate the expression of several genes involved in the calcium handling independent of melanoma disease." (PMID 39834851, 2024).
multiple myeloma (2 papers, 2020 to 2022). "Inhibition of CT-like activity with ixazomib (IXA), a proteasome inhibitor currently used in patients with multiple myeloma, prevents RyR2 degradation during ischemia and significantly improves cell survival after ischemia/reperfusion." (PMID 32453773, 2020). "We have previously shown that ixazomib (IXA), a proteasome inhibitor used for treating multiple myeloma, effectively reduced the size of the infarct produced by global ischemia in isolated rat hearts and prevented degradation of the sarcoplasmic reticulum calcium release channel RyR2." (PMID 32453773, 2020).
neuroblastoma (2 papers, 2016 to 2017). Neuroblastoma (NB) is the most common solid, extracranial childhood tumor. "We report here that RyR2 undergoes post-translational modifications (phosphorylation, oxidation, and nitrosylation) in SH-SY5Y neuroblastoma cells expressing the β-amyloid precursor protein (βAPP) harboring the familial double Swedish mutations (APPswe)." (PMID 28476886, 2017).
prostate carcinoma (2 papers, 2019 to 2024). A carcinoma that arises from epithelial cells of the prostate gland. "RYR2 mutations have previously been identified in several cancers, but through comparative analysis guided by progression modeling, it was revealed as an important event in prostate cancer." (PMID 39347576, 2024). "Gene Hsa.11632 (RYR1), together with RYR2 stimulates apoptosis of prostate cancer cells." (PMID 31150453, 2019).
respiratory failure (2 papers, 2014 to 2020). The significant impairment of gas exchange within the lungs resulting in hypoxia, hypercarbia, or both, to the extent that organ tissue perfusion is severely compromised. "Mouse knock-out experiments have shown that RyR1 and RyR2 have a critical role in physiology and development: mice deficient in RyR1 died perinatally due to respiratory failure while those lacking RyR2 died during the early stages of embryonic development." (PMID 32899693, 2020).
amyloid (1 paper, 2012). "The goal of this study was to examine whether sub-chronic treatment with the RyR antagonist dantrolene in AD mouse models would normalize ER Ca2+ signaling disruptions, reduce RyR2 expression, stabilize downstream synaptic transmission and plasticity expression, and reduce amyloid pathology." (PMID 23284867, 2012).
aortic insufficiency (1 paper, 2009). "RyR2 expression has been reported to be decreased in HF by 25% in rabbit or ∼30% in canine models of aortic insufficiency, 48% in a canine model of chronic HF by pacing and 35% in human heart." (PMID 19345240, 2009). "Other studies, measuring the FKBP12.6 that can be immunoprecipitated with the solubilised RyR2 complex, demonstrated a decrease in the FKBP12.6/RyR2 ratio of 50% (paced dog) or 65% (human HF) or 38% (rabbit aortic insufficiency)." (PMID 19345240, 2009).
autoimmune disease (1 paper, 2023). A disorder resulting from loss of function or tissue destruction of an organ or multiple organs, arising from humoral or cellular immune responses of the individual to their own tissue constituents. "The therapeutic effects that RyR2-deficient Tconvs conveyed in multiple inflammatory and autoimmune models suggest that targeting of RyR2 activity may have therapeutic potential for autoimmune diseases, which are often associated with low numbers or dysfunction of Tregs." (PMID 38099491, 2023). "The observation that RyR2 inhibition equips Tconvs with suppressive function (albeit with more limited capacity than Tregs in vivo) opens new opportunities for therapeutic targeting of the RyR2 pathway to heighten Tconv suppressive function in autoimmune diseases and graft-versus-host disease." (PMID 38099491, 2023).
bladder cancer (1 paper, 2020). "Among the top ten genes, PIK3CA, RYR2, and KMT2C were highly expressed in the bladder cancer compared to normal bladder tissue (P < 0.001)." (PMID 33344221, 2020).
blood pressure (1 paper, 2023). "Mutations in dystrophin in VSMCs lead to significantly increased expression of KCNQ5 and RYR2, potentially resulting in low blood pressure in DMD patients." (PMID 37569835, 2023).
breast invasive carcinoma (1 paper, 2022). "A trend of stratification by RYR2 mutations can also be found in breast invasive carcinoma (BRCA) and LUAD." (PMID 36167878, 2022).
Cachexia (1 paper, 2024). Severe weight loss, wasting of muscle, loss of appetite, and general debility related to a chronic disease. "Based on these findings, we propose that ACT may exert its anti-cachexia effects through the regulation of inflammatory response and energy metabolism via multiple targets, including CYP3A4, CYP19A1, CYP2E1, TNF, BCL-2, RYR2, and ATP2A1." (PMID 39872045, 2024).
colon adenocarcinoma (1 paper, 2022). "The average number of RyR2 mutations per person was generally higher than that for RYR1 and RYR3, mostly strikingly in LUAD, LUSC and colon adenocarcinoma (COAD)." (PMID 36167878, 2022).
conduction disorders (1 paper, 2021). "Similar to our differential gene expression analysis, we focused on alternative splicing events affecting genes involved in regulation of cardiac ion transport and previously implicated in conduction disorders — Scn5a, Kcnd3, Kcnip2, Ryr2, and Camk2d." (PMID 33497365, 2021).
esophageal cancer (1 paper, 2024). A primary or metastatic malignant neoplasm involving the esophagus. "Patients with RYR2 mutations in esophageal cancer exhibit higher tumor mutation load (TMB), better prognosis, and enhanced immune checkpoint expression." (PMID 38200058, 2024).
euthyroid sick syndrome (1 paper, 2016). Abnormal thyroid function tests, low triiodothyronine with elevated reverse triiodothyronine, in the setting of non-thyroidal illness. "Rats with HF developed euthyroid sick syndrome (ESS) and treatment with T4 restored the T3 values to the Sham level and increased Serca2 and Ryr2 gene expression, thereby demonstrating a possible benefit of T4 treatment for heart function in ESS associated with HF." (PMID 27737323, 2016).
focal epilepsy (1 paper, 2022). A seizure caused by a localized disorder. "In the present study, we used WES to identify a novel truncating mutation [c.12670G > T/p.(Glu4224*)] of RYR2 in a child with focal epilepsy." (PMID 36340715, 2022). "We propose that RYR2 mutations may manifest with either CPVT or focal epilepsy, which may depend on the selective participation of RYR2 receptors in the heart or brain." (PMID 36340715, 2022). "Here, we present a novel heterozygous mutation of RYR2 in a child with focal epilepsy." (PMID 36340715, 2022). "Therefore, these cases demonstrated that RYR2 may be a causative gene of focal epilepsy." (PMID 36340715, 2022). "Additionally, This study identified a novel mutation of RYR2 in a 3-year and 4-month-old boy with focal epilepsy using the whole-exome sequencing (WES), supplementing the phenotypic spectrum of RYR2 mutations." (PMID 36340715, 2022).
genetic generalized epilepsy (1 paper, 2024). A generalized epilepsy that is understood to have a genetic etiology. "The RyR2 A77T mutation has been reported as a potential cause in a case of adult-onset genetic generalized epilepsy, where the patient never described any cardiac symptoms and had repeatedly normal cardiac investigations including normal exercise stress tests." (PMID 39777228, 2024).
gynecological cancers (1 paper, 2020). "Furthermore, TTN, MUC16, CSDM3, RYR2, USH2A, and SYNE1 were frequently mutated in gynecological cancers but not in the MSK-IMPACT samples, suggesting that they play specific roles in the development of gynecological malignancies." (PMID 32626534, 2020).
hepatitis B infection (1 paper, 2014). "HCC derived from hepatitis B infection demonstrated a significantly higher rate of OR8K3, PRL and RYR2 mutations (22% vs. 0%, 22% vs. 1%, 22% vs. 2%; p = 0.008, p = 0.022, p = 0.041, respectively)." (PMID 24988079, 2014).
HIV-1 infection (1 paper, 2026). The type species of lentivirus and the etiologic agent of acquired immunodeficiency syndrome (AIDS). "However, little is known about whether expression and/or activities of the major SR Ca2+ release and uptake proteins, namely RyR2 and SERCA2 are altered during HIV-1 infection, and whether these changes are prevented/reversed with antiretroviral drug treatment." (PMID 41516391, 2026).
homeostasis (1 paper, 2023). "However, the combined heterozygous RYR2-A1855D and SCN10A-Q1362H variants in the proband iPS-CMs resulted in accentuated Ca2+ homeostasis disorders, action potential prolongation and susceptibility to early afterdepolarizations at high stimulus frequencies." (PMID 37122207, 2023).
Huntington disease (1 paper, 2022). Huntington disease (HD) is a rare neurodegenerative disorder of the central nervous system characterized by unwanted choreatic movements, behavioral and psychiatric disturbances and dementia. "Furthermore, there are observations that fixing RyR2-mediated ER Ca2+ leak with the S107 improves cognitive and locomotor function in a murine model of Huntington’s disease." (PMID 35399287, 2022).
hypospadias (1 paper, 2018). Hypospadias is the displacement of the urethral meatus on the ventrum of the penis. "Finally, three other deletions were found respectively in SPAG16, playing a role in the axoneme of the sperm, RYR2, whose mutations have been associated to cardiac diseases and ATF3, a candidate gene for hypospadias." (PMID 30042735, 2018).
lymphedema (1 paper, 2021). Excess fluid collection in tissues, causing swelling. "However, DANT has not received attention as an anti-lymphedema therapeutic, largely because the contribution of RYRs to lymph muscle contraction is regarded as minimal and the identity of the RYR subtypes (RYR1, RYR2, and RYR3) expressed by LMCs is unresolved." (PMID 34483938, 2021).
Myalgia (1 paper, 2017). "This mechanistic scenario is further bolstered by the discovery that a number of single nucleotide polymorphisms (e.g., SLCO1B1, SLCO2B1 and RYR2) associated with statin myalgia and myositis were observed with increased frequency among patients with statin myalgia." (PMID 28771594, 2017).
neuropathy (1 paper, 2019). A disorder affecting the nervous system that manifests with pain, tingling, numbness, and/or muscle weakness. "HuD is upregulated and contributes to pain hypersensitivity to mechanical and cold stimulation in antiretroviral-evoked painful neuropathy by regulating spinal ryanodine receptor-2 or GAP43 or contributes to thermal hot hyperalgesia in oxaliplatin-induced neuropathy by regulating GAP43." (PMID 31013625, 2019).
non-small cell lung carcinoma (1 paper, 2025). A group of at least three distinct histological types of lung cancer, including non-small cell squamous cell carcinoma, adenocarcinoma, and large cell carcinoma. "For example, the RYR2 protein is related to cardiac pacing, and mutation of the RYR2 gene is related to patient survival in non-small cell lung cancer." (PMID 41154723, 2025).
oral cancer (1 paper, 2024). "First, neither the Taiwanese database nor the samples in this study were representative enough to determine the disease pathways for the oral cancer–RYR2 association the wider population." (PMID 39408657, 2024). "There may be a relationship between oral cancer risk and the RYR2 rs12594 variant in the context of consumption behaviors." (PMID 39408657, 2024). "There was a significant correlation between RYR2 rs2779359 and the clinical status of oral cancer patients in our study." (PMID 39408657, 2024). "Further research is needed to understand the link between RYR2 SNP rs2779359 and other common somatic genetic changes in oral cancer." (PMID 39408657, 2024). "Finally, RYR2 SNP rs2779359 not only plays a role in both the prognosis and diagnosis of oral cancer but is also likely an important predictive factor for recurrence, response to treatment, and medication toxicity." (PMID 39408657, 2024). "However, RYR2 SNP rs2779359 was also related to oral cancer progression in a subgroup of patients with specific clinical stage and tumor size." (PMID 39408657, 2024).
pancreatic disorders (1 paper, 2021). "Abnormal type 2 ryanodine receptor (RyR2) function, associated to mutations (ryanopathies) or pathological remodeling, has been reported, not only in cardiac diseases, but also in neuronal and pancreatic disorders." (PMID 34725342, 2021).
Parkinson disease (1 paper, 2022). A progressive degenerative disorder of the central nervous system characterized by loss of dopamine producing neurons in the substantia nigra and the presence of Lewy bodies in the substantia nigra and locus coeruleus. "CPNQ targets huntingtin and α-synuclein to lower their pathological effects in cellular models of Huntington’s and Parkinson’s diseases, respectively, and we show here that this compound significantly inhibited only RyR1 (with an inhibitory trend on RyR2) at low [Ca2+]." (PMID 34793835, 2022).
rectal tumors (1 paper, 2025).
rhabdomyolysis (1 paper, 2013). Necrosis or disintegration of skeletal muscle often followed by myoglobinuria. "In a recent GWAS study, an intronic variant (rs2819742) in RYR2 was significantly associated with cerivastatin-associated rhabdomyolysis at the a priori p value threshold of 4 × 10−7 (p = 1.74 × 10−7)." (PMID 23829686, 2013). "An additional copy of the minor allele of the RYR2 variant was associated with a reduced risk of rhabdomyolysis (odds ratio (OR) = 0.48; 95% confidence interval (CI) = 0.36 to 0.63)." (PMID 23829686, 2013).
Sjogren syndrome (1 paper, 2021). An autoimmune disorder in which immune cells attack and destroy the glands that produce tears and saliva. "MiR-143-3p can affect epithelial cell homeostasis by targeting SERCA2b, RyR2, and AC9 in Sjogren's syndrome." (PMID 34211501, 2021).
Thromboembolism (1 paper, 2022). The formation of a blood clot inside a blood vessel that subsequently travels through the blood stream from the site where it formed to another location in the body, generally leading to vascular occlusion at the distant site. "Due to a lack of blood DNA samples and detailed clinical information on I: 1, II: 1 and II: 2 before death, we can’t evaluate the influence of RYR2 p.T858M on the risk of ARVC/D, thromboembolism, ECG abnormality and sudden death." (PMID 35526016, 2022).
thyroid deficiency (1 paper, 2024). "Quantitation of total RyR2 clusters within a defined cell area (ROI of 3.0 × 108 nm2) showed that thyroid deficiency (PTU) resulted in a significant decrease in cluster number compared with EU control and that this was subsequently normalized by T3 treatment alone (PTU + T3)." (PMID 39365674, 2024). "In our earlier work studying effects of thyroid deficiency on TTs and ion channel organization, similar 2-D STORM images were analyzed using hierarchical density-based clustering of RyR2 localizations with further constraints applied to cluster size." (PMID 39365674, 2024).
thyrotoxic periodic paralysis (1 paper, 2024). Thyrotoxic periodic paralysis (TPP) is a rare neurological disease characterized by recurrent episodes of paralysis and hypokalemia during a thyrotoxic state. "Furthermore, gene set enrichment analysis revealed associations of LRP1B and RYR2 with thyrotoxic periodic paralysis." (PMID 39770638, 2024).
triple-negative breast carcinoma (1 paper, 2022). An invasive breast carcinoma which is negative for expression of estrogen receptor (ER), progesterone receptor (PR), and human epidermal growth factor receptor 2 (HER2). "In addition, it has been proven that RYR2 was associated with malignant progression of triple-negative breast cancer." (PMID 36578478, 2022).
Type 1 diabetes (1 paper, 2024). "Our previous studies showed that RyR2 represents the most common type of non-enzymatic post-translational modification (PTM) by RCS/ROS contribute to the heterogeneity in RyR2 activity in a rat model of Type 1 diabetes." (PMID 38961333, 2024).
uterine carcinosarcoma (1 paper, 2022). A usually aggressive malignant neoplasm arising from the uterine corpus and less often the cervix. "The results showed that the mutational status of RYR2 did not stratify the survival in all cancer types, while significant stratification can be found in bladder urothelial carcinoma (BLCA) (P = 0.00071), LUSC (P = 0.036) and uterine carcinosarcoma (UCS) (P = 0.034)." (PMID 36167878, 2022).
vascular tumor (1 paper, 2023). "CRC patients with serosa invasion and vascular tumor thrombus are characterized by high RyR2 expression." (PMID 36453019, 2023). "Taken together, high RyR2 expression in primary CRC tissue was correlated with serosa invasion and vascular tumor thrombus formation, and predicted a poor prognosis." (PMID 36453019, 2023).
viral infection (1 paper, 2023). "To establish functional equivalency of Ryr2–/– Tconvs and Tregs, we tested their behaviors in viral infection, allergic response, autoimmune colitis, and tumor development, with comparison to similarly infused purified Tregs." (PMID 38099494, 2023).